KRAS (KRas proto-oncogene, GTPase)
Diseases named in the same sentence as KRAS in open-access papers (continued):
Sharing a sentence is not in itself a finding about the gene and the disease.
tumor (continued). "Together, our findings demonstrate that although NS-LUAD tumours generally lack the high mutational burden KRAS mutant tumours, they require fewer copy number changes than their EGFR mutant counterparts to progress." (PMID 41509216, 2025). "Kirsten rat sarcoma viral oncogene homolog (KRAS) has been the most studied oncogene that has the highest mutation rate in the vast majority of tumour types, including PDAC (>90%) and CRC (~50%)." (PMID 38773787, 2025). "CAR-T therapies target tumor-associated antigens including KRAS G12D, mesothelin, EGFR, HER2, and CLDN18.2, with early trials reporting partial responses and stable disease." (PMID 40806185, 2025). "Further, this finding provides an explanation as to why NS-LUAD tumours on the SD trajectory have fewer genomic alterations than those on the NSD trajectories: these tumours are significantly enriched for KRAS mutations." (PMID 41509216, 2025). "Mutant KRAS overexpression causes oxidative stress in mitochondria and oncogenic KRAS‐expressing cells show increased glycolytic activity, which promotes malignant tumor progression." (PMID 40046406, 2025). "The activation of the KRAS signaling pathway has been linked to aggressive tumor behavior and poor prognosis in ACC patients." (PMID 40282330, 2025). "While KRAS mutations activate proliferative signaling pathways, tumor formation appears to require additional genetic alterations such as APC mutations, which disrupt tumor suppressor mechanisms." (PMID 41285904, 2025). "Despite all the successes, the acquisition of drug resistance by cells, as well as the mutational status of the downstream protein KRAS, reduces the tumor response to therapy." (PMID 41009766, 2025). "When survival was compared between the KRAS mutation dosage groups with similar tumor purity levels, patients with a high KRAS mutation dosage experienced shorter RFS than those with a low dosage." (PMID 39779977, 2025). "Its clinical aggressiveness is driven by profound chemoresistance and near-universal KRAS mutations, which reprogram tumor metabolism toward mitochondrial respiration, redox adaptation, and anabolic biosynthesis." (PMID 41155556, 2025). "This study highlights the prognostic significance of HIF-1α, LOX and ITGA5 expression in the tumor microenvironment, particularly in the context of KRAS/NRAS/BRAF mutation status." (PMID 39857068, 2025). "Among NS-LUAD on the SD trajectory, KRAS mutations are the most prominent, occurring in 22/65 tumours (34%) and representing the strongest association with the SD trajectory in this group (OR for enrichment in SD = 32.1, FDR = 2.8×10−13)." (PMID 41509216, 2025). "KRAS gene mutations seem to be more common in tumours located in the right colon or in the descending colon, in different studies." (PMID 39996841, 2025).
tumor (continued). "Consistently, KRAS mutations were associated with a higher number of TAMs and macrophage reprogramming via tumor-derived lactate and colony stimulating factor in colorectal cancer." (PMID 40524071, 2025). "In relation to the tumour extension (T), KRAS mutation was mostly associated with T3, as it was detected in 36 T3 tumours (66.7%), followed by T4, as it was detected in 10 T4 tumours (18.5%), and T2, as it was detected in 8 T2 tumours (14.8%)." (PMID 39996841, 2025). "By following tumor growth, we found that tumors in NS and T cells groups grew promptly, while 100 μg HLA-A2/KRAS G12V-CD3 BiTE modified activated T cells caused significantly tumor regression." (PMID 41472736, 2025). "In contrast, inhibitors targeting the more prevalent KRAS G12D mutation have demonstrated promising tumor regression in preclinical studies and are currently being evaluated in clinical trials." (PMID 41303394, 2025). "Because the mutation dosage obtained using TS data represents the variant allele frequency of the KRAS mutation, it is significantly associated with tumor purity." (PMID 39779977, 2025). "Following primary tumour resection, a marked reduction was observed in both the copy number and mutation abundance score of KRAS G12V/D variants within metastatic lesions." (PMID 40740862, 2025). "For the KRAS G12D mutation, the RMC-9805 showed selective inhibition in KRAS G12D human cancer cell lines in vitro and tumor models in vivo." (PMID 40805153, 2025). "KRAS gene mutations are correlated with tumor aggressiveness and poor prognosis, and they are acquired in 40–45% of CRC patients, mainly at the transition from low- to high-grade dysplasia." (PMID 39941740, 2025). "Molecular markers, such as KRAS mutations and circulating tumor DNA (ctDNA) profiles, are beginning to illuminate paths for personalized therapy selection." (PMID 40572765, 2025). "Tumor invasion depth, KRAS or driver gene mutations were associated with patients carrying the MICA-129 Met/Met genotype." (PMID 41431073, 2025). "That is, CRC tumours with oncogenic KRAS plus high WNT activity are associated with significantly elevated canonical NF-κB signalling, consistent with our Drosophila data." (PMID 41188521, 2025). "For instance, KRAS G12D tumors exhibited more niches rich in T cells but largely devoid of tumor cells, a characteristic associated with poorer clinical outcomes." (PMID 40485603, 2025). "For example, mutant KRAS alters the apoptotic machinery, making tumor cells less susceptible to DNA damage induced by cytotoxic agents." (PMID 40361439, 2025). "It was through molecular analyzes in clinical studies that the acquisition of secondary KRAS mutations was most frequently identified; mainly through analysis of circulating tumor DNA." (PMID 39936820, 2025). "Previous studies have demonstrated that KRAS mutations in NSCLC can activate downstream signaling pathways that promote PD-L1 expression in tumor cells." (PMID 40936915, 2025). "The frequency of KRAS variants including G12D, G12V, and Q61H in each tumor type differed from those reported previously, suggesting that the distribution of KRAS mutations differs among racial groups." (PMID 40499463, 2025). "ARS-1620 induced more significant tumor growth inhibition and regression in patient-derived xenografts (PDXs) harboring the KRAS G12C mutation than in other KRAS-mutated PDXs." (PMID 40597785, 2025). "T cells targeting a KRAS mutation can induce durable tumor regression in some patients with metastatic epithelial cancer." (PMID 39846249, 2025).
tumor (continued). "Common mutations in the KRAS gene include amino acid substitutions G12C, G12D, and G12R, each linked to different tumor types." (PMID 39858030, 2025). "As is the case with the presented patient, tumor findings of mutant KRAS and the loss of STK11 confer a poor prognosis." (PMID 41257133, 2025). "This assessment revealed that almost all primary tumor material and related PDOs, with the exception of those of patient 4, contained a nonsynonymous single nucleotide variant in the KRAS gene, which is one of the key PDAC driver mutations." (PMID 41141365, 2025). "LBDA successfully identified KRAS mutations in 37.29% of tumor samples, achieving 88% sensitivity and 100% specificity compared to the NGS method, demonstrating its high accuracy, sensitivity, and translational potential for clinical CRC mutation detection." (PMID 40422048, 2025). "By identifying genetic mutations (e.g., EGFR, KRAS) and predicting tumor behavior, AI enables more precise preoperative planning and risk stratification, guiding the extent of resection, lymph node dissection, or multimodal therapy selection." (PMID 40283559, 2025). "Across the pan-cancer landscape, KRAS G12A is also relatively uncommon, accounting for approximately 4% of all KRAS mutations detected, a frequency observed consistently in pan-tumor tissue data and liquid genotyping assays." (PMID 41300966, 2025). "Oncogenic KRAS frequently engenders an immunosuppressive milieu through recruitment of suppressive immune subsets such as myeloid-derived suppressor cells (MDSCs), tumor-associated macrophages (TAMs), and regulatory T cells." (PMID 41170373, 2025). "Having identified that RalGAPβ deficiency has additional cellular effects in comparison with κB-Ras loss, we wanted to understand how this would affect tumor development triggered by KRas mutation." (PMID 40490362, 2025). "The G12D mutation constitutively activates KRAS, directly causing uncontrolled cell proliferation, tumor formation, and alterations in the tumor microenvironment." (PMID 41516002, 2025). "The tumor microenvironment associated with KRAS is often inflammatory, which increases the occurrence and development of cancer." (PMID 41309533, 2025). "We established a scoring system by integrating three variables: maximal tumor diameter at baseline CT, CA 19-9 level, and KRAS G12 mutation dosage based on TS data." (PMID 39779977, 2025). "Mechanistically, the oncogenic KRAS variant activates inflammatory cytokines, chemokines and downstream signalling pathways to promote tumour development and invasiveness." (PMID 39820726, 2025). "KRAS mutations play a significant role in shaping the tumor microenvironment and influencing cancer progression." (PMID 39806421, 2025). "KRAS mutations play a pivotal role in orchestrating an immunosuppressive tumor microenvironment by promoting the pathological recruitment of Tregs, MDSCs, and tumor-associated neutrophils via the upregulation of cytokine and chemokine expression." (PMID 40303413, 2025). "Recent clinical trials have reported that metastatic CRC with tumor-promoting mutations in KRAS, PI3KCA, and BRAF is resistant to anti-EGFR therapy." (PMID 38542151, 2024).
tumor (continued). "KRAS mutations promote and maintain tumor growth through the RAS/MAPK pathway and are thought to be present in approximately 25% of all human cancers." (PMID 39156972, 2024). "At last, a mechanism by which KRas mutated tumors elaborate tumor resistance to KRas inhibitors was shown to involve ERK1/2-mediated phosphorylation of IRE1, thus preventing its degradation by the ERAD machinery." (PMID 38494075, 2024). "Nevertheless, mutations in genes such as KRAS, as well as low tumor mutation burden can also be seen." (PMID 39415766, 2024). "To validate how KRAS mutations affect the interaction between microbes and tumor cells in complex organisms, we intratumorally injected ETBF into xenografted nude mouse tumors." (PMID 39523457, 2024). "ADAM8, being an extracellular matrix protease, can be regulated by these pathways, leading to its elevated expression in the KRAS 12/13-mutated tumor group." (PMID 39329961, 2024). "In the other 28 patients, only circulating tumor DNA was analyzed at the time of acquired resistance, and 22 patients demonstrated the original KRAS G12C mutation." (PMID 38756650, 2024). "Testing for KRAS mutations is possible from tumor DNA isolated from tumor tissue, bronchial brush smears, plasma or pleural fluid (cfDNA analysis), using either a single-gene PCR-based approaches, classical or a next-generation sequencing." (PMID 38953007, 2024). "Given their pivotal role in tumor initiation and progression, KRAS mutation targeting represents a promising therapeutic strategy." (PMID 39673361, 2024). "Despite some discrepancies, several studies have demonstrated the prognostic significance of KRAS mutations in both tumor tissue and liquid biopsies from PDAC patients." (PMID 39456638, 2024). "To test if the combination of tumor size and KRAS mutational status impacts the risk of death, we defined an interaction term including both variables." (PMID 38884086, 2024). "Depending on the specific KRAS mutation in the tumor tissue, differences in progression free survival (PFS) were observed in the same study." (PMID 39457426, 2024). "The findings revealed that the genes influenced by MZ1 were linked to the regulation of multiple tumor-related processes and activities, including the G2M checkpoint, epithelial-mesenchymal transition, E2F targets, and KRAS signaling." (PMID 38365636, 2024). "In the metastatic setting, it has been reported that the clinical activity of ICI is lower in tumors with actionable driver alterations (except for KRAS mutations), though they can induce tumor regression in some cases." (PMID 38611088, 2024). "We extended our analysis to multivariate Cox regression models, integrating clinical variables such as patient age, tumor stage, and KRAS mutation status with endogenous LTR10 expression and gene set scores." (PMID 39018396, 2024). "The key challenge of this kind of liquid biopsy in PDAC is the fact that the discovery rate of KRAS-mutated cftDNA in plasma is usually lower than in matching tumor tissue." (PMID 38255325, 2024). "And in terms of HALLMARK pathways, overexpressed BCAT1 was also positively associated with tumor-related and angiogenesis-related pathways, such as KRAS signaling pathway, PI3K/Akt/mTOR signaling pathway, and Angiogenesis pathway." (PMID 38309289, 2024).
tumor (continued). "Recent studies correlated T2WI radiomic features with KRAS status, obtaining significant results in differentiating wild-type from mutated KRAS tumours." (PMID 39272969, 2024). "Cancers with KRAS mutations are particularly lethal due to their role in promoting rapid cell proliferation and resulting in highly aggressive tumor phenotype." (PMID 39850800, 2024). "For example, some reports showed a high concordance (77%) of KRAS variant between tumor tissues and plasma, and concordance between tissue and blood ctDNA ranged from 63.2% (APC) to 85.5% (BRAF) in CRC." (PMID 38777950, 2024). "Nevertheless, KRASG12C mutations account for only around 15% of KRAS-mutated cancers, and there are no approved KRAS inhibitors for the majority of patients with tumours containing other common KRAS mutations." (PMID 38589574, 2024). "Each of the three adenocarcinomas demonstrated somatic KRAS mutations which were maintained between primary tumor and xenografts." (PMID 39123450, 2024). "The surface marker Sca-1, which was first used to target the (BASC), identifying tumor-propagating cells (TPCs) in genetically engineered mice models of NSCLC bearing KRAS mutation." (PMID 39547513, 2024). "Their research revealed that loss of MTH1 function impairs the growth of KRAS tumor cells, while overexpression of MTH1 reduces sensitivity to the compound SCH51344." (PMID 38357002, 2024). "Specifically, AEs related to neoplasms were predominantly associated with lung malignancies, all of which were consistent with the therapeutic indications of KRAS G12C mutation inhibitor." (PMID 39263575, 2024). "In contrast, two patients still experienced positive clinical outcomes, although they had HRDneg tumor samples with amplifications of KRAS and CCNE1, respectively, typically associated with resistance to PARPi." (PMID 39591206, 2024). "On the other hand, new biomarkers such as circulating tumour DNA (ctDNA) measurement and peripheral KRAS mutations represent promising methods to identify high-risk patients with R-PDAC and guide individualized treatment." (PMID 39329454, 2024). "To evaluate differences between primary tumor size from CT scans at diagnosis stratified by KRAS mutational status, we used the Mann-Whitney U test." (PMID 38884086, 2024). "Although KRAS mutations are prevalent across tumor types, it’s clear that there is heterogeneity with regard to responses." (PMID 38576709, 2024). "The KRAS mutation plays a major role in the development of tumor progression and resistance to treatment." (PMID 38846975, 2024). "MRTX1133 was also evaluated in immunocompromised mice bearing tumor xenografts with the KRASG12D mutation to determine its effect on KRAS-mediated signaling and characterize its in vivo antitumor activity." (PMID 39456549, 2024). "Olomorasib (LY3537982) showed a range of anti-tumor activity from complete regression to significant tumor growth inhibition in xenograft models harboring KRAS G12C mutation." (PMID 39337530, 2024). "There was a lack of significant association between mlTNB clusters with age, race, sex, PAAD subtypes, KRAS mutation status and tumour purity." (PMID 39427051, 2024). "The laboratory analysis revealed that, of the 33 samples from the tumor biopsies, 9 (27.3%) had mutations in the KRAS gene and 5 (15.1%) in the NRAS gene, in the genetic positions studied." (PMID 39816392, 2024). "From the analysis of the training cohort, four independent prognostic risk factors, namely tumor marker score, KRAS mutation, primary lymph node metastasis, and tumor burden score were identified on which a WCH‐nomogram was constructed." (PMID 38698687, 2024).